CYP1A2 (cytochrome P450 family 1 subfamily A member 2)
Diseases named in the same sentence as CYP1A2 in open-access papers (continued):
Sharing a sentence is not in itself a finding about the gene and the disease.
melanoma (2 papers, 2021 to 2023). A malignant, usually aggressive tumor composed of atypical, neoplastic melanocytes. "The present study determined the mRNA levels of the cytochromes CYP1A1, CYP1A2 and CYP2E1, as well as the protein levels of cytochrome CYP1A1 in melanoma cells." (PMID 36533319, 2023). "Ability of melanoma cells to metabolize dacarbazine was determined by expressional analysis of CYP1A1, CYP1A2, CYP2E1 followed by CYP1A1 protein level evaluation by the ELISA method." (PMID 36533319, 2023).
obstructive sleep apnea (2 papers, 2019 to 2022). "In this study, we aimed to determine the effects of intermittent hypoxia (IH) on hepatic cytochrome P450 1A2 (CYP1A2) expression and the pharmacokinetics of CYP1A2-mediated aminophylline and warfarin in vitro and in a rabbit model of obstructive sleep apnea." (PMID 35529917, 2022).
oral cancer (2 papers, 2016 to 2022). "The involvement of CYP1A1/CYP1A2 and its inhibition by α-naphthoflavone on ANE-induced events suggest that possibly metabolic activation of ANE components is necessary for some of the ANE-induced carcinogenic events and increase the risk of OSF and oral cancer." (PMID 26919242, 2016).
osteoporosis (2 papers, 2025). A condition of reduced bone mass, with decreased cortical thickness and a decrease in the number and size of the trabeculae of cancellous bone (but normal chemical composition), resulting in increased fracture incidence. "Furthermore, an imbalanced gut microbiota can alter the activity of liver metabolic enzymes, such as CYP1A2, slowing caffeine metabolism and leading to its accumulation, thereby increasing osteoporosis risk." (PMID 40584094, 2025). "Our study revealed significant interactions between CYP1A2 and various drugs, suggesting its potential impact on the efficacy of osteoporosis treatments." (PMID 40918403, 2025).
psychosis (2 papers, 2024). "Similarly, smoking status has been associated previously with increased dose, which may be due to the effect of smoking on CYP1A2 activity, an enzyme also involved in the metabolism of certain drugs for psychosis, such as olanzapine and clozapine." (PMID 39344086, 2024). "The study only explored one route of psychosis drug metabolism using CYP2D6, and despite it playing a major role in metabolism, other cytochrome P450 enzymes, such as CYP1A2, CYP2C9/19 or CYP3A4/5 offer alternate metabolism routes for psychosis drugs." (PMID 38494658, 2024).
rheumatoid arthritis (2 papers, 2018 to 2022). A chronic, systemic autoimmune disorder characterized by inflammation in the synovial membranes and articular surfaces. "When LEF is used for the treatment of rheumatoid arthritis (RA), individuals carrying the CYP1A2*1F CC gene are more likely to have a 9.7-fold higher risk of overall toxicity than those carrying the CYP1A2*1F A allele." (PMID 35935867, 2022).
somnolence (2 papers, 2023 to 2025). "Moreover, other authors reported that ciprofloxacin inhibits CYP1A2, with an increase in the blood concentration of substrate drugs (e.g., olanzapine and tizandine) and an increase in ADRs (e.g., QT prolongation and somnolence, respectively)." (PMID 38132493, 2023).
tuberculosis (2 papers, 2022 to 2023). A chronic, recurrent infection caused by the bacterium Mycobacterium tuberculosis. "The metabolic inducers included the anticonvulsant phenytoin, a moderate inducer of CYP1A2; the anti-tuberculosis drug rifampicin, a strong inducer of CYP3A; and the sedative drug dichloralphenazone." (PMID 35456623, 2022).
alcoholic fatty liver disease (1 paper, 2024). Lipid infiltration of the hepatic parenchymal cells that is due to alcohol abuse. "The expression of CYP1A2 was attenuated among individuals with non-alcoholic fatty liver disease." (PMID 38287425, 2024).
amyotrophic lateral sclerosis (1 paper, 2022). Amyotrophic lateral sclerosis (ALS) is a neurodegenerative disease characterized by progressive muscular paralysis reflecting degeneration of motor neurons in the primary motor cortex, corticospinal tracts, brainstem and spinal cord. "While, non-constantly, both the ADORA2A rs5760423 and CYP1A2 rs762551 variants have been associated with PD, CYP1A2 rs762551 polymorphism has also been associated with amyotrophic lateral sclerosis and blepharospasm." (PMID 36430879, 2022).
Anorexia (1 paper, 2023). Lack of desire to eat (loss of appetite). "Our leave-one-out analyses found that exclusion of the variant rs12903896 resulted in deflation towards the null for the CYP1A2 anorexia estimate, but resulted in more extreme estimates, further away from the null, for the other outcomes." (PMID 37553644, 2023).
Apnea (1 paper, 2022). Lack of breathing with no movement of the respiratory muscles and no exchange of air in the lungs. "Although the calculated dose from milk exposure is in line with the maintenance infusion dose used for apnea treatment, accumulation of theophylline can occur, especially in premature infants due to the lower capacity of their CYP1A2 clearance pathway, which can lead to adverse effects." (PMID 35652056, 2022).
Ascites (1 paper, 2013). Accumulation of fluid in the peritoneal cavity (between the layers of the peritoneum that lines the abdomen). "Normalization of signal intensity to the amount of protein loaded per lane showed that CYP1A1 and CYP1A2 were induced to similar levels in healthy and non-ascitic cirrhotic rats, whereas their induction was significantly lower in rats with ascites." (PMID 23626760, 2013).
bladder urothelial carcinoma (1 paper, 2024). "The results of the analysis demonstrate a significant elevation in CYP1A2 expression within bladder urothelial carcinoma when compared to normal tissue." (PMID 39039510, 2024).
chronic myeloid leukemia (1 paper, 2022). "Olverembatinib (HQP1351) is a third-generation BCR-ABL tyrosine kinase inhibitor for the treatment of chronic myeloid leukemia (CML) (including T315I-mutant disease), exhibits drug-drug interaction (DDI) potential through cytochrome P450 (CYP) enzymes CYP3A4, CYP2C9, CYP2C19, CYP1A2, and CYP2B6." (PMID 36582520, 2022).
colitis (1 paper, 2022). Inflammation of the colon. "It is possible that the accumulation of AhR ligands in Cyp1a1-/- mice may not be at the same levels compared to triple Cyp knockout mice (lack of CYP1A1, CYP1A2 and CYP1B1 enzymes) to render the beneficial activities against DSS-induced colitis." (PMID 36159798, 2022).
colorectal adenoma (1 paper, 2007). An adenoma that arises from the colon or rectum. "Previously, SNPs in both CYP1A1 and CYP1A2 have been associated with colorectal adenomas and carcinomas, therefore the observation of some relationship between CYP1A2 rs2069522 and risk in our study is not without precedent." (PMID 17615053, 2007).
Crohn disease (1 paper, 2021). A gastrointestinal disorder characterized by chronic inflammation involving all layers of the intestinal wall, noncaseating granulomas affecting the intestinal wall and regional lymph nodes, and transmural fibrosis. "In Crohn’s disease, S-verapamil concentration was higher than R-verapamil while the opposite was found in normal conditions and higher plasma levels of propranolol were found in Crohn’s with reduced metabolic activities of CYP1A2, 2D6 and 2C19." (PMID 34867341, 2021).
enterocolitis (1 paper, 2023). An inflammatory process affecting the small intestine and colon. "It is also found that downregulation of CYP1A2 is observed during inflammation, whereas AhR activation protects intestinal epithelium from enterocolitis by promoting CYP1A2 expression, and that indole derivatives activate AhR to promote IL-22 secretion, which boosts intestinal mucosal defense." (PMID 37344888, 2023).
fibrosarcoma (1 paper, 2021). A malignant mesenchymal fibroblastic neoplasm affecting the soft tissue and bone. "More specifically, we demonstrated that RRM2 and CYP1A2 play a vital role in the resistance of human fibrosarcoma to DOX." (PMID 34799689, 2021). "However, more studies using clinical fibrosarcoma patient samples and in vivo animal models are needed to uphold the association of piR-39980 and its two targets, RRM2 and CYP1A2, with positive responses of fibrosarcoma patients to DOX." (PMID 34799689, 2021). "Our finding showed that piR-39980 could attenuate the DOX resistance by repressing the expression of RRM2 and CYP1A2 in DOX-resistant fibrosarcoma cells and hence could be a potential therapeutic agent for improving the clinical response of fibrosarcoma patients to DOX." (PMID 34799689, 2021). "To investigate the role of piR-39980/CYP1A2 in modulating chemoresistance in fibrosarcoma, we performed an MTT assay and found that the cell viability of the DOX-treated cell was increased by 40% upon CYP1A2 overexpression (P < 0.05)." (PMID 34799689, 2021). "This study reveals that piR-39980 could reduce fibrosarcoma resistance to DOX by modulating RRM2 and CYP1A2, implying that piRNA can be used in combination with DOX." (PMID 34799689, 2021).
generalized tonic-clonic seizures (1 paper, 2014). "An increased tardive dyskinesia severity was observed in patients with the A allele of the CYP1A2*1C polymorphism and in another study with CYP1A2 (C→A), while the CYP1A2 −163C > A polymorphism is associated with clozapine-induced generalized tonic-clonic seizures." (PMID 24555493, 2014).
heart cancer (1 paper, 2008). "As breast volume may be associated with heart cancer risk, we studied the relationship between breast volume, CYP1A2*1F and coffee intake." (PMID 18813311, 2008).
hereditary hemochromatosis (1 paper, 2023). An inherited metabolic disorder characterized by iron accumulation in the tissues. "As another example, UGT1A1*28, UGT1A1*60, and cytochrome P450 1A2 (CYP1A2) rs762551 were associated with a pazopanib-related increase in bilirubin, while SNPs in hereditary hemochromatosis gene (HFE) were associated with increased levels of ALT." (PMID 37370844, 2023).
Hypoalbuminemia (1 paper, 2018). The concentration of albumin in the blood circulation is below the lower limit of normal. "Hamon-Wilcot and coauthors investigated the activity of the CYP1A2 subunit of the P450 cytochrome in individuals above the age of 65 years with weight loss and hypoalbuminemia." (PMID 30103687, 2018).
hypothyroidism (1 paper, 2021). Abnormally low levels of thyroid hormone. "In addition, the expression of Ehhadh, Haao, and Cyp1A2 were up-regulated and Cat, Aldh2, and Ehhadh were down-regulated in hypothyroidism rats." (PMID 33959028, 2021).
ileus (1 paper, 2021). Decrease in peristalsis in the absence of a mechanical bowel obstruction. "Clozapine intoxication presenting with symptoms such as myoclonus, drowsiness, neutropenia, or (paralytic) ileus commonly occurs after a reduction of tobacco consumption or during infection, both resulting in a reduced CYP1A2 activity and thus decreased clozapine metabolism." (PMID 34071813, 2021).
intrahepatic cholestasis (1 paper, 2025). A cholestasis characterized by impairment of the bile flow caused by obstruction located in the liver. "Pathogenic prediction for five missense variants of the ESR2, CYP1A2, and CYP17A1 genes in 249 Han Chinese people with intrahepatic cholestasis of pregnancy." (PMID 40933484, 2025).
lipid metabolism disorders (1 paper, 2023). "Integrated analysis results indicated that the downregulation of Cytochrome P450 1A2 (CYP1A2) expression was closely linked to lipid metabolism disorders." (PMID 37035728, 2023).
malaria (1 paper, 2018). Malaria is a serious and sometimes fatal disease caused by a parasite that commonly infects a certain type of mosquito which feeds on humans. "Malaria can downregulate hepatic levels of cyp1a2, cyp2e1, and cyp3a11 mRNAs, causing prolongation of midazolam sleeping time and a slower clearance of chlorzoxazone." (PMID 30477109, 2018).
metabolic syndrome (1 paper, 2025). A cluster of metabolic risk factors for CARDIOVASCULAR DISEASES and TYPE 2 DIABETES MELLITUS. "Our study showed that patients with metabolic syndrome who have the AA genotype for the rs762551 polymorphism in the CYP1A2 gene and drink coffee in moderate amounts (1–2 cups/day) have significantly higher levels of vitamin B12 and folate compared to those with AC or CC genotypes." (PMID 40710550, 2025). "The aim of this study is to investigate the interaction between CYP1A2-related caffeine metabolism and vitamin B12/folate status in individuals diagnosed with metabolic syndrome." (PMID 40710550, 2025).
myxoma (1 paper, 2023). A benign soft tissue neoplasm characterized by the presence of spindle and stellate cells, lobulated growth pattern, and myxoid stroma formation. "RNA-seq of the two myxoma tissues and a normal atrial tissue showed that the expression of CYP1A2 was at an extremely low level without any change, while the expression of KIF1C was at a moderate level with an average decrease of 66% in myxoma tissues." (PMID 37452081, 2023).
Neurodevelopmental delay (1 paper, 2025). "Polymorphisms in CYP3A4, CYP2C19, and CYP1A2 could impair detoxification of environmental toxicants, while dysfunction in CYP2E1 and CYP2D6 has been linked to oxidative stress and mitochondrial impairment—both implicated in neurodevelopmental delays." (PMID 40386062, 2025).
periapical abscess (1 paper, 2021). "In the periapical abscess, MAPT and CYP1A2 genes had a prediction of alternative alleles of 0.79 and 0.73 from A>G (rs7521) and C>A (rs762551), respectively." (PMID 34539639, 2021).
Shock (1 paper, 2022). The state in which profound and widespread reduction of effective tissue perfusion leads first to reversible, and then if prolonged, to irreversible cellular injury. "Furthermore, our results show maximal impairment of CYP1A2 activity measured with LiMAx® 24 h after the start of CytoSorb® treatment, especially in patients with septic shock and extremely elevated IL-6 levels." (PMID 36289602, 2022).
Skin rash (1 paper, 2020). A red eruption of the skin. "Correlation between CYP1A2 polymorphisms and severity of skin rash was observed, together with the correlation between the development of diarrhea and SNPs in ABCB1 and CYP3A5." (PMID 32457635, 2020). "The polymorphism of CYP1A2 was significantly associated with the severity of skin rash, and the development of diarrhea was associated with SNPs in ABCB1 and CYP3A5." (PMID 32457635, 2020). "Findings from our present study showed that the polymorphism of CYP1A2 was the only statically significant covariate responsible for erlotinib induced skin rash (p = 0.029)." (PMID 32457635, 2020). "The severity of skin rash was only associated with the polymorphism of rs762551 in CYP1A2 (p=0.029)." (PMID 32457635, 2020). "The polymorphisms of CYP1A2 plays an important role in the severity of skin rash, and the development of diarrhea was associated with SNPs in ABCB1 and CYP3A5." (PMID 32457635, 2020). "The polymorphism of CYP1A2 may have a significant influence on the pharmacokinetic of erlotinib, which resulted in the variation of the severity of skin rash in our study." (PMID 32457635, 2020). "Other factors additional to CYP1A2 activity may also influence erlotinib induced skin rash." (PMID 32457635, 2020).
substance abuse (1 paper, 2025). The use of a drug for a reason other than which it was intended or in a manner or in quantities other than directed. "Other potential confounding factors include acute stress at admission and timing of assessments, duration of illness, change in smoking intensity during hospitalization, dietary CYP1A2 modulators, and substance abuse history (other than nicotine)." (PMID 41011234, 2025).
testicular cancer (1 paper, 2014). A primary or metastatic malignant neoplasm that affects the testis. "Furthermore, other studies showed that low activity of CYP1A2 was associated with risk of testicular cancer and PCa." (PMID 25355624, 2014).
vascular ectasia (1 paper, 2018). "For example, nodes such as CYP1A1, CYP1A2, CYP1B1 in module 1 belonged to cytochrome P450 (CYPs) family, which could enrich in epoxygenase P450 pathway and relate with cardiovascular-related functions such as vascular ectasia." (PMID 30158870, 2018).
Wilson disease (1 paper, 2021). A very rare inherited multisystemic disease presenting non-specific neurological, hepatic, psychiatric or osseo-muscular manifestations due to excessive copper deposition in the body. "Gene expression of analyzed enzymes ranged between 18 and 65% compared to control group and significantly lower protein content of CYP1A1, CYP1A2, CYP2C8, CYP2C9, CYP3A4 and CYP3A5 enzymes was observed in Wilson’s disease." (PMID 34117631, 2021).